NAA10 (N-alpha-acetyltransferase 10, NatA catalytic subunit)
Diseases named in the same sentence as NAA10 in open-access papers (continued):
Sharing a sentence is not in itself a finding about the gene and the disease.
cancer (continued). "NAA10-mediated protein acetylation plays a crucial role in regulating key cellular processes relevant to cancer development, including cell cycle, migration, apoptosis, autophagy, differentiation, and proliferation." (PMID 40558489, 2025). "To narrow down potential NAA10-acetylated targets in cancer, we integrated the 1082 NAA10-correlated proteins with previously identified NAA10 substrates from numerous experimental models." (PMID 40558489, 2025). "The transcriptional and signaling regulation of NAA10 in cancer has been broadly investigated both in vitro and in vivo." (PMID 40558489, 2025). "This study demonstrated the feasibility of pharmacologically targeting NAA enzymatic pockets, providing a foundation for the future development of more specific and potent inhibitors to dissect NAA10′s function in cancer and assess its therapeutic relevance." (PMID 40558489, 2025). "NAA10 is overexpressed in various types of cancer, affecting the overall survival rate and disease recurrence of cancer patients." (PMID 36568377, 2022). "Although the efforts to elucidate the biological function of NAA10, it remains disputed regarding its roles in cancer." (PMID 35366056, 2022). "Under glutamine deprivation or hypoxic condition, mTOR-mediated NAA10 phosphorylation at S228 residue is downregulated, resulting in the activation of an acetyltransferase activity of NAA10 and the promotion of protective autophagy processes in cancer cells." (PMID 33126484, 2020). "Autoacetylation of NAA10 at K136 residue, which is essential for enzymatic activity of NAA10, is rapidly stimulated by anticancer drug treatment, leading to the activation of cellular stress response and the protection of cancer cells against cell death." (PMID 33126484, 2020). "Accordingly, the expressions of NAA10 are highly upregulated in various types of cancer tissues compared to its adjutant normal tissues." (PMID 33126484, 2020). "On the basis of this reason, it is reasonable to expect that the role of NAA10 is critical for cancer cells." (PMID 33126484, 2020). "Here we summarize the current knowledge regarding the biological functions of NAA10 in cancer progression and provide the potential usage of NAA10 as a prognostic marker for cancer progression." (PMID 33126484, 2020). "Innumerable studies have demonstrated that the expression level of NAA10 in tumor tissues is closely correlated with disease progression and clinical outcomes of various cancers." (PMID 33126484, 2020). "Several research groups have demonstrated that the expression levels of NAA10 in cancer tissues are considerably correlated with the progression, metastasis, and the survival." (PMID 33126484, 2020). "Molecular mechanistic studies have revealed that NAA10-mediated protein acetylation plays a crucial role in regulating cellular events that are significant for cancer development, such as cell cycle progression, cell death, migration, and autophagy." (PMID 33126484, 2020). "Based on above referenced studies, this review discusses the possibility of NAA10 as a prognostic cancer biomarker and describes the biological functions of NAA10 in cancer progression." (PMID 33126484, 2020). "It’s of note that we and others have reported an oncogenic role of Naa10 in diverse types of cancers." (PMID 27910960, 2016). "In mammalian cells, most studies about Naa10’s function are mainly focused on its relationship with cancer." (PMID 27910960, 2016). "Here we first unravel NTN1 and its receptor UNC5B as the key downstream targets of Naa10 in cancer cell line." (PMID 27910960, 2016). "Though there is a growing body of evidence showing that NAA10 plays a pivotal role in cancer development, the function of NAA10 is controversial." (PMID 26646451, 2016). "Naa10 protein is a major modulator of cell growth and differentiation that has been recently reported to be important in cancer progression." (PMID 27910960, 2016).
cancer (continued). "Furthermore, we discuss the therapeutic potential and challenges of targeting NAA10 in cancer, and propose future research directions to better understand its multifaceted roles in health and disease." (PMID 40558489, 2025). "Nevertheless, while evidence supports a potential KAT function for NAA10, particularly in cancer models, further biochemical and structural studies are needed to definitively characterize its lysine acetylation activity, as well as its underlying structural and biochemical mechanisms." (PMID 40558489, 2025). "Furthermore, we discuss the potential clinical implications and future prospects of NAA10 as a therapeutic target for cancer treatment." (PMID 40558489, 2025). "We next tried to determine whether NAA10 expression regulates ferroptosis sensitivity in cancer cells." (PMID 39742570, 2025). "In addition, accumulating evidence suggests that NAA10 can function either as an oncogene or a tumor suppressor, depending on the cancer type or cellular context." (PMID 40558489, 2025). "These NAA10 N-terminally acetylated proteins are involved in various biological pathways and processes, and their alterations may contribute to cancer growth and progression." (PMID 40558489, 2025). "•NAA10 catalyzes lactylation of NSUN2 rendering cancer cell ferroptosis resistant." (PMID 39742570, 2025). "In addition, previous studies have shown that NAA10 expression and activity are regulated at multiple levels in human cancers, contributing to its oncogenic and/or tumor-suppressive roles depending on the cellular context." (PMID 40558489, 2025). "Similarly, in the 12 tumor types analyzed from the CPTAC proteomics dataset, NAA10 exhibited significantly elevated protein expression levels (p < 0.05) in 11 cancer types compared to normal controls." (PMID 40558489, 2025). "NAA10 is an acetyltransferase that acetylates proteins at the posttranslational level, and it has been demonstrated by many studies to be a potential prognostic marker for cancer progression." (PMID 36803975, 2023). "NAA10 may play diverse roles in different types of cancer cells or different stages during cancer tumorigenesis, and thus, identifying cancer‐type‐specific targets will help to understand the role of NAA10 in a certain cancer type." (PMID 35366056, 2022). "This evidence all points NAA10 toward a promising biomarker for cancer prognosis." (PMID 33126484, 2020). "The sensitivity of cancer cells to pharmacological targeting of NAA10 could therefore be lower in tumours, such as testicular germ cell carcinoma, where NAA11 is consistently present." (PMID 32942614, 2020). "Whether NAA10 retains the opposite functions in different cancer types or under distinct conditions requires further study." (PMID 33126484, 2020). "However, the roles of NAA10 in cancer tissues seem to be very complicated because the overexpression of NAA10 is closely associated with poor outcomes in HCC and CRC, but with better outcomes in BCa and OSCC." (PMID 33126484, 2020). "The development of selective inhibitors of hARD1/NAA10 KAT activity may be potentially useful for cancer therapy." (PMID 32013195, 2020). "NAA10 is increasingly recognized as an important regulator in multiple cellular processes and the development of a variety of cancers, but the regulatory mechanisms of such processes is largely unknown." (PMID 26646451, 2016). "Among them, GCN1, a protein involved in regulating protein synthesis and other cellular processes in response to amino acid starvation, stands out as a robust candidate and may serve as a valuable marker for investigating the functions, roles, and mechanisms of NAA10 in various cancer models." (PMID 40558489, 2025). "Similarly to NAA10-related syndromes, the biological roles of NAA10 in cancer likely involve both its acetylation-dependent mechanisms (including Nα- and Nε-acetyltransferase activities) and acetylation-independent mechanisms, depending on the cellular context." (PMID 40558489, 2025).
cancer (continued). "Since the major functions of NAA10 involve regulating protein folding, localization, complex formation, and degradation, changes in NAA10 protein abundance in cancer cells are likely to influence the levels of other proteins, some of which may be direct substrates of its acetyltransferase activity." (PMID 40558489, 2025). "Interestingly, as illustrated in the shinyDepMap plot, NAA10 and MYC display similar efficacy and selectivity scores in CRISPR and shRNA screens, further supporting a regulatory association between NAA10 and MYC in certain cancers." (PMID 40558489, 2025). "Interestingly, NAA10′s effects on metastasis appear to be context-dependent; it may either inhibit or promote cancer cell motility depending on the specific acetylation targets and the signaling pathways involved." (PMID 40558489, 2025). "Moreover, the adaptive upregulation of NAA11 could be a mechanism for cancer cells to reduce the toxicity of NAA10 inhibition." (PMID 32942614, 2020). "In addition to NAA10, other NATs play roles in cancer progression." (PMID 33126484, 2020). "Moreover, as hARD1/NAA10 stands out as an attractive drug target for cancer treatment, our finding may be helpful for the development of hARD1/NAA10 inhibitors, which can be applied to cancer therapy." (PMID 32013195, 2020). "Additionally, it is worthwhile to investigate the functions of NAA10, be it as an oncoprotein or a tumor suppressor, that could be rendered by cancer specific microenvironment." (PMID 33126484, 2020). "Given the controversial role of NAA10 in cancer invasion and metastasis, particularly reports of its function as a metastasis suppressor in several studies, these negatively correlated proteins may represent downstream targets of NAA10 that contribute to its role in metastatic regulation." (PMID 40558489, 2025). "Although NAA10 has been shown to function as a KAT in various studies, particularly in the context of cancer, this activity remains a subject of ongoing debate." (PMID 40558489, 2025). "Since NAA10 and its auxiliary subunit NAA15 are overexpressed in certain cancers, protein degraders targeting NAA10 or NAA15 offer a promising strategy to eliminate NAA10 in tumors where its overexpression drives tumorigenesis." (PMID 40558489, 2025). "In the TCGA pan-cancer cohort, IRAK1 expression positively correlated with DKC1 (R = 0.54), FAM58A (R = 0.51), NAA10 (R = 0.54), SLC10A3 (R = 0.55), and UBLA4 (R = 0.62)." (PMID 35669566, 2022). "We identified the top five related genes (DKC1, FAM58A, NAA10, SLC10A3, UBL4A) that mostly correlated with IRAK1 by GEPIA2.0; the heatmap displayed the correlation in pan-cancers." (PMID 35669566, 2022). "All these results suggest that the physiological roles of NAA10 could be dynamically and transiently regulated by protein modifications and interactions over time and space, which should not be overlooked to understand the physiological roles of NAA10 in cancer." (PMID 33126484, 2020). "In this study, in silico and immunohistochemistry analyses showed that Naa10 transcripts or the Naa10p protein were more highly expressed in primary and metastatic PCa cancer tissues compared to adjacent normal tissues and non-metastatic cancer tissues, respectively." (PMID 32719332, 2020).
tumor (18 papers, 2009 to 2025). "These multilayered regulatory mechanisms underscore the complex control of NAA10 expression and function in tumor progression." (PMID 40558489, 2025). "Analysis of phosphoproteomics data from the CPTAC dataset revealed alterations in phosphorylation levels at several sites of NAA10 protein across multiple tumor types, supporting the regulation of NAA10 activity by kinases and/or phosphatases." (PMID 40558489, 2025). "Accumulating evidence demonstrated that NAA10 interacts with various transcription factors to regulate the expression of tumour‐related target genes." (PMID 35366056, 2022). "Taken together, this study elucidated that NAA10, as a tumour suppressor, inhibited tumorigenesis, migration and invasion in OSCC." (PMID 35366056, 2022). "Studies have shown that, Naa10 participates in the autophagy, apoptosis, and proliferation of tumor cells." (PMID 35515126, 2022). "N‐α‐Acetyltransferase 10 (NAA10) was reported to be involved in tumour invasion and metastasis in several of tumours." (PMID 35366056, 2022). "By binding to PIX proteins, NAA10 inhibited Cdc42/Rac1 activity and, therefore, suppressed tumour metastasis." (PMID 35366056, 2022). "Several studies have demonstrated the contribution of the KAT activity of hARD1/NAA10 to tumor development." (PMID 32013195, 2020). "Mechanistic studies have revealed diverse molecular mechanisms of NAA10 and defined NAA10 as a double-faced player, an oncoprotein, and a tumor suppressor." (PMID 33126484, 2020). "Studies show that NAA10 is a stable protein that is expressed in a broad range of tissues and tumor cell lines." (PMID 26646451, 2016). "For example, Naa10 (the catalytic subunit of NatA complex) has been proposed to behave both as an oncoprotein and as a tumor suppressor." (PMID 26666750, 2016). "Almost all the tumor tissues had a higher NAA10 mRNA level compared to their individually matched normal adjacent tissues, suggesting that NAA10 upregulation may be a critical event during ESCA carcinogenesis." (PMID 36433943, 2022). "NAA10 mRNA levels were significantly higher in ESCA tumor tissues compared to normal tissues." (PMID 36433943, 2022). "Specifically, the growth rates of tumour xenografts were elevated by stable knockdown of NAA10." (PMID 35366056, 2022). "Higher NAA10 expression was observed in ESCA tumor tissues compared to normal tissues." (PMID 36433943, 2022). "The expression levels of NAA10 in HCC were positively correlated with tumor recurrence." (PMID 33126484, 2020). "However, earlier studies have suggested that NAA10 may function as a tumor suppressor in certain tumor types or cellular contexts." (PMID 40558489, 2025). "However, other studies found that NAA10 may serve as a tumour suppressor." (PMID 35366056, 2022). "They proved that NAA10 interacts with DNA methyltransferase 1 (DNMT1) thereby silencing E-cadherin, a tumor suppressor gene." (PMID 33126484, 2020). "Given that phosphorylation is a key regulatory mechanism influencing protein activity, including the acetyltransferase activity of NAA10, we also analyzed phosphoproteomics data from the CPTAC dataset to compare NAA10 phosphorylation between tumor and normal samples." (PMID 40558489, 2025). "They showed that NAA10 interacts with matrix metalloproteinase-2 (MMP-2) via its acetyltransferase domain and in turn promotes the stabilization of MMP-2 protein, leading to the increases in cell invasion and tumor metastasis." (PMID 33126484, 2020).
genetic disease (4 papers, 2020 to 2022). "Over the past decade, many NAA10 missense variants have been reported as causative of genetic disease in humans." (PMID 32698785, 2020). "Inherited or de novo missense variants in NAA10 have also been identified as causative of genetic disease in humans." (PMID 33255974, 2020). "Several NAA10 variants are associated with genetic disorders." (PMID 32973342, 2021). "Furthermore, NAA10 missense variants have in recent years emerged as causative of genetic disease, collectively known as NAA10-related syndrome." (PMID 32973342, 2021). "Several inherited and de novo NAA10 variants have been associated with genetic disease in humans." (PMID 33255974, 2020). "The mechanisms underlying genetic diseases resulting from pathogenic NAA10 variants remain elusive." (PMID 33255974, 2020).
infection (3 papers, 2021 to 2025). The state of being infected such as from the introduction of a foreign agent such as serum, vaccine, antigenic substance or organism. "After infection, the yield loss of the NAA15‐OE plants was higher than that of the NAA15‐RNAi and NAA10‐RNAi plants." (PMID 40820884, 2025). "Next, CAL 27 and SCC‐15 cells with stable interference of NAA10 expression were generated by lentiviral infection of shRNA targeting NAA10, whose target was identical to that of siNAA10‐2." (PMID 35366056, 2022).
brain disorder (1 paper, 2024). A disease affecting the brain or part of the brain. "The authors speculated in their paper that the various phenotypes of the mice (growth retardation, embryonic lethality, brain disorder, and maternal-effect lethality) might be caused by a previously unappreciated role for Naa10 in DNA methylation and genomic imprinting." (PMID 38713657, 2024).
NAA10 also shares sentences with these, for which no sentence is quoted: Lenz microphthalmia syndrome (3 papers); autism spectrum disorder (2); cardiac arrhythmia (2); colorectal cancer (2); gastric cancer (2); hepatocellular carcinoma (2); liver cancer (2); non-small cell lung carcinoma (2); adenocarcinoma (1); Anophthalmia (1); autoimmune disease (1); Autoimmunity (1); Beckwith-Wiedemann syndrome (1); brain malformations (1); cardiomyopathy (1); Cornelia de Lange syndrome (1); cryptorchidism (1); epilepsy (1); esophageal squamous cell carcinoma (1); exophthalmos (1); follicular lymphoma (1); gynaecological diseases (1); heart disease (1); hypophysis (1); hypoxic-ischemic encephalopathy (1); Immunodeficiency (1); intellectual disability syndrome (1); Intraventricular hemorrhage (1); Kabuki syndrome (1); KBG syndrome (1).
A further 24 diseases each share a sentence with NAA10 in 1 paper.